CYP4A27P (cytochrome P450 family 4 subfamily A member 27, pseudogene)
Synonyms: CYP4A-se3[12]
Gene: Unprocessed pseudogene on chromosome 1 (47,000,898 to 47,001,087, reverse strand). Ensembl gene ENSG00000261593.
Diseases named in the same sentence as CYP4A27P in open-access papers:
CYP4A27P is named in the same sentence as 1 disease in open-access papers, as found by Europe PMC text mining. Sharing a sentence is not in itself a finding about the gene and the disease.
CYP4A27P shares sentences with these, for which no sentence is quoted: lung carcinoma (1 paper).